PRMT1 (protein arginine methyltransferase 1)
Diseases named in the same sentence as PRMT1 in open-access papers (continued):
Sharing a sentence is not in itself a finding about the gene and the disease.
influenza (1 paper, 2017). An acute viral infection of the respiratory tract, occurring in isolated cases, in epidemics, or in pandemics; it is caused by serologically different strains of viruses (influenzaviruses) designated A, B, and C, has a 3-day incubation period, and usually lasts for 3 to 10 days. "That we measured equal expansion of influenza specific CD8+ T cells in control and Prmt1f/fCD23Cre mice following infection rules out technical issues or systemic immune suppression in the Prmt1-deficient group." (PMID 29026071, 2017).
intestinal cancer (1 paper, 2020). "Crossing these mice with intestine-specific Villin-Cre or tumor-developing Apcmin mice, could be an elegant way to further study the role of PRMT1 in IEC differentiation and maturation and to investigate the therapeutic potential of PRMT1 inhibition for the treatment of intestinal cancer." (PMID 33575256, 2020).
iron deficiency (1 paper, 2024). "Deferoxamine (DFO)/iron deficiency and miR-503 downregulate PRMT1 mRNA levels." (PMID 40018367, 2024). "Furthermore, iron chelators and iron deficiency can effectively reduce PRMT1 levels." (PMID 40018367, 2024).
kidney injury (1 paper, 2025). Trauma to the kidney. "In this study, mice with specific deletion or overexpression of PRMT1 in tubular epithelial cells were developed, and a CaOx crystal-induced kidney injury mouse model was established." (PMID 40744915, 2025). "Simultaneously, TEC-specific PRMT1 KO mice were used to construct a CaOx crystal-induced kidney-injury mouse model, and the KO efficiency was detected using WB and DNA agarose gel electrophoresis." (PMID 40744915, 2025). "Our study elucidated a novel PRMT1/UBE2m/NEDD4/PPARγ signaling axis that drives renal lipid metabolic dysfunction in CaOx crystal-induced kidney injury." (PMID 40744915, 2025).
kidney stone (1 paper, 2025). "However, the role of PRMT1-mediated arginine methylation in kidney stone-induced renal injury remains unclear." (PMID 40744915, 2025).
laryngeal carcinoma (1 paper, 2024). Carcinoma that arises from the laryngeal epithelium. "The expression of PRMT1 in laryngeal cancer tissues was detected by RT-qPCR experiment, and the results showed that the mRNA expression of PRMT1 in laryngeal cancer tissues was significantly higher than that in adjacent tissues." (PMID 39741976, 2024). "Current research has found that the expression of PRMT1 is increased in laryngeal carcinoma tissues." (PMID 39741976, 2024). "All these results indicated that PRMT1 knockdown inhibited the proliferation, migration and invasion of laryngeal cancer cells." (PMID 39741976, 2024). "The present study aimed to investigate how PRMT1-mediated H4R3me2a methylation affects the proliferation, migration and invasion of laryngeal cancer cells and to verify the role of NCOA5 in this process." (PMID 39741976, 2024). "The results showed that after knocking down PRMT1, the level of H4R3me2a significantly decreased, and the proliferative and migratory/invasive abilities of laryngeal carcinoma cells were weakened." (PMID 39741976, 2024). "After PRMT1 knockdown, the expression of H4R3me2a in laryngeal cancer cells was significantly decreased, and the cell proliferation, migration and invasion abilities were weakened." (PMID 39741976, 2024). "PRMT1 and NCOA5 play important roles in the development of laryngeal carcinoma and provide new insights for developing therapeutic strategies targeting PRMT1 and NCOA5." (PMID 39741976, 2024). "Additionally, transcriptome sequencing of laryngeal carcinoma cells with PRMT1 knockdown revealed a significant decrease in NCOA5 expression." (PMID 39741976, 2024). "NCOA5 may maintain normal levels of H4R3me2a by promoting the recruitment of PRMT1 to specific gene loci or enhancing its activity, thereby regulating the proliferation and migration of laryngeal carcinoma cells." (PMID 39741976, 2024). "The expression of PRMT1 and NCOA5 was inhibited by siRNA mediated gene knockdown in laryngeal cancer cells." (PMID 39741976, 2024). "PRMT1, as a protein arginine methyltransferase, may directly affect the stability or function of NCOA5 through methylation modification, thus influencing the proliferation, migration, and invasive abilities of laryngeal carcinoma cells." (PMID 39741976, 2024). "In this study, we found that PRMT1 expression is significantly increased in laryngeal carcinoma tissues compared to adjacent non-tumor tissues, suggesting that PRMT1 may be involved in the development of laryngeal carcinoma." (PMID 39741976, 2024).
lentivirus infection (1 paper, 2016). Virus diseases caused by the Lentivirus genus. "We stably overexpressed PRMT1 in MCF10A cells (designated MCF10A-PRMT1) by using lentivirus infection, in which the PRMT1 expression level was comparable to the endogenous PRMT1 expression in MDA-MB-231." (PMID 26813495, 2016).
lymphoid leukaemia (1 paper, 2024). "Noteworthy, PRMT1 has been recently found highly expressed in acute myeloid and lymphoid leukaemia." (PMID 38350611, 2024).
mantle cell lymphoma (1 paper, 2023). Mantle cell lymphoma is a rare form of malignant non-Hodgkin lymphoma affecting B lymphocytes in the lymph nodes in a region called the ``mantle zone''. "Moreover, high PRMT1 expression was associated with reduced survival in DLBCL and mantle cell lymphoma patients." (PMID 37310381, 2023).
Myocardial fibrosis (1 paper, 2024). "We then analyzed myocardial fibrosis in heart sections via Sirius Red staining, and the qualitative results revealed that the accumulation of collagen in the ISO + PRMT1 inhibition group was greater than that in the ISO group." (PMID 39659162, 2024).
myotonic dystrophy type 1 (1 paper, 2025). Steinert disease, also known as myotonic dystrophy type 1, is a muscle disease characterized by myotonia and by multiorgan damage that combines various degrees of muscle weakness, arrhythmia and/or cardiac conduction disorders, cataract, endocrine damage, sleep disorders and baldness. "Given our observation that DB75 modulates PRMT1-mediated RBM15-SF3B1 splicing regulators, it could be possible that DB75 also regulates RNA splicing in myotonic dystrophy type 1 through PRMT1 inhibition." (PMID 39826691, 2025).
nasopharyngeal carcinoma (1 paper, 2025). A carcinoma arising from the nasopharyngeal epithelium. "In nasopharyngeal carcinoma, LMP1 promotes the interaction between PRMT1 and PGC-1α, leading to its methylation, stabilization, and enhanced anoikis resistance, thereby increasing metastatic potential." (PMID 41204384, 2025). "PRMT1 also stabilizes PGC-1α through methylation, which cooperates with STAT3 to transcriptionally activate PD-L1, promoting immune evasion in nasopharyngeal carcinoma." (PMID 41204384, 2025).
oncocytoma (1 paper, 2019). "Additionally, we found PRMT1 expression as more common in benign tumors, such as oncocytoma." (PMID 31655611, 2019).
osteoporosis (1 paper, 2018). A condition of reduced bone mass, with decreased cortical thickness and a decrease in the number and size of the trabeculae of cancellous bone (but normal chemical composition), resulting in increased fracture incidence. "Our results suggest that PRMT1 plays an important role in the progression of osteoporosis and that it might be a good therapeutic target for postmenopausal osteoporosis." (PMID 30154485, 2018). "Suppression of PRMT1 by estrogen appears to inhibit excessive osteoclast formation, suggesting it could be a potential therapeutic target for treating osteoporosis." (PMID 30154485, 2018). "Thus, PRMT1 can be a therapeutic target to treat the development and progression of osteoporosis." (PMID 30154485, 2018). "In addition, OVX-induced osteoporosis improved in PRMT1 haploinsufficient (PRMT1+/-) mice, and these results suggest that PRMT1 may contribute to osteoclast differentiation and osteoporosis." (PMID 30154485, 2018). "Although the important function that PRMT1 plays in various tissues is being increasingly recognized, its role in receptor activation of NF-κB ligand (RANKL)-induced osteoclastogenesis or osteoporosis has not yet been described." (PMID 30154485, 2018).
Parkinson disease (1 paper, 2025). A progressive degenerative disorder of the central nervous system characterized by loss of dopamine producing neurons in the substantia nigra and the presence of Lewy bodies in the substantia nigra and locus coeruleus. "Additionally, emerging research has begun to elucidate the potential role of PRMT1 in chronic liver diseases (CLDs), such as nonalcoholic fatty liver disease (NAFLD), neurodegenerative diseases (NDs) including Parkinson's disease (PD), and immune‐related diseases." (PMID 41256732, 2025).
Peritoneal Fibrosis (1 paper, 2025). Disorder characterized by a wide range of structural changes in PERITONEUM, resulting from fibrogenic or inflammatory processes. "In the current study, we demonstrate that inhibition of PRMT1 alleviates peritoneal fibrosis by inhibiting the demethylation of H4R3 thereby suppressing the activation of EGFR and downstream signaling pathways." (PMID 40612681, 2025). "However, the role of PRMT1 in peritoneal fibrosis has never been reported before." (PMID 40612681, 2025). "Therefore, we believe that PRMT1 promotes peritoneal fibrosis through the regulation of EGFR, but EGFR may not be its only substrate protein during the process of peritoneal fibrosis." (PMID 40612681, 2025).
plasma cell leukemia (1 paper, 2023). An aggressive plasma cell neoplasm characterized by the presence of neoplastic plasma cells in the peripheral blood. "Besides, analysis of dataset GSE13591 revealed significant upregulation of PRMT1 expression in MM (n = 133, p = 0.016), with even more pronounced elevation in plasma cell leukemia (PCL) (n = 9, p < 0.0001)." (PMID 37558663, 2023).
postmenopausal osteoporosis (1 paper, 2018). Metabolic disorder associated with fractures of the femoral neck, vertebrae, and distal forearm. "In the present study, we provide evidence that PRMT1 is critical for RANKL-induced osteoclastogenesis in vitro and that it contributes to bone loss in ovariectomized (OVX) mice, which is a representative animal model for postmenopausal osteoporosis." (PMID 30154485, 2018).
prostate adenocarcinoma (1 paper, 2017). "Only prostate adenocarcinoma was found to have low levels of PRMT1 mRNA expression." (PMID 29113301, 2017).
Pulmonary hemorrhage (1 paper, 2025). Pulmonary hemorrhage is a bleeding within the lungs. "Strikingly, the endothelial PRMT1 knockout (KO) mice developed pulmonary hemorrhage associated with EC dysfunction, characterized by increased inflammation and NF‐κB activation." (PMID 40135804, 2025). "The loss of PRMT1 in ECs led to pulmonary hemorrhage, compromised barrier function, increased inflammation, and fibrosis, all of which are hallmarks of COPD‐related vascular pathology." (PMID 40135804, 2025). "Mice with endothelial‐specific PRMT1 deletion develop pulmonary hemorrhage, inflammation, and apoptosis, driven by excessive nuclear factor kappa B activation." (PMID 40135804, 2025). "PRMT1 ablation in ECs (KO) for 2 weeks displayed a mild phenotype of pulmonary hemorrhage and lung mass increase compared to vehicle‐treated Prmt1fl/fl; Cdh5ERT2–Cre (Con) mice." (PMID 40135804, 2025).
Renal insufficiency (1 paper, 2023). A reduction in the level of performance of the kidneys in areas of function comprising the concentration of urine, removal of wastes, the maintenance of electrolyte balance, homeostasis of blood pressure, and calcium metabolism. "Protein arginine methyltransferase‐1 (PRMT1) is a key regulator of renal insufficiency." (PMID 37525933, 2023).
Renal neoplasm (1 paper, 2019). The presence of a neoplasm of the kidney. "Therefore, we may speculate that RUNX1/PRMT1 co-expression may be significant for the favorable behavior of renal neoplasms." (PMID 31655611, 2019).
retinoblastoma (1 paper, 2025). A malignant tumor that originates in the nuclear layer of the retina.
sarcopenia (1 paper, 2023). Progressive decline in muscle mass due to aging which results in decreased functional capacity of muscles. "The current study highlights the importance of Prmt1 in motor neurons and muscle maintenance, with implications for sarcopenia." (PMID 37342629, 2023). "Thus, Prmt1 is a potential target for the prevention or intervention of sarcopenia and neuromuscular dysfunction related to aging." (PMID 37342629, 2023).
Sepsis (1 paper, 2023). Sepsis is defined as life-threatening organ dysfunction caused by a dysregulated host response to infection. "In the present study, sepsis induced PRMT1 expression in the renal, and inhibition of PRMT1 decreased the serum level of Cr and BUN and the expression of NGAL, a marker of renal injury, demonstrating that PRMT1 contributes to SI‐AKI." (PMID 37525933, 2023). "This suggests that PRMT1 inhibition alleviates sepsis‐induced apoptosis in the kidneys, particularly in renal tubular epithelial cells." (PMID 37525933, 2023). "Whether PRMT1 contributes to renal inflammation need to be investigated because renal tissue is exposed to severe inflammatory cytokine storm during sepsis, and inflammation is an important mechanism for fibrosis." (PMID 37525933, 2023). "Thus, in the present study, we utilized the cecal ligation and perforation (CLP) murine model, a classic model of SI‐AKI, to assess whether the progression of sepsis‐induced renal injury is epigenetically regulated by PRMT1 through the TGF‐β1/Smad3 and IL‐6/STAT3 pathways." (PMID 37525933, 2023). "Our results showed that inhibition of PRMT1 downregulates the expression of COX‐2, IL‐6, sIL‐6, and p‐STAT3 in the kidney, which was induced by sepsis, revealing the regulation role of PRMT1 in inflammation and the IL‐6 trans‐signaling pathway." (PMID 37525933, 2023). "Additionally, the inhibition of PRMT1 was demonstrated to reverse these EMT‐related proteins and suppresses sepsis‐induced apoptosis in renal tissues." (PMID 37525933, 2023). "The results of the western blot showed that sepsis induced by CLP increased the expression of cleaved caspase‐3 in the renal tissues, and AMI repressed the cleavage of caspase‐3 (P < 0.01), suggesting that AMI might reduce cell apoptosis by inhibiting PRMT1 molecule in the kidneys." (PMID 37525933, 2023).
small cell lung carcinoma (1 paper, 2024). Small cell lung cancer (SCLC) is a highly aggressive malignant neoplasm, accounting for 10-15% of lung cancer cases, characterized byrapid growth, and early metastasis. "Additionally, PRMT1 methylation of SOX2 at arginine 43 has been linked to increased stemness and chemotherapy resistance in small cell lung cancer (SCLC)." (PMID 38326807, 2024).
squamous cell carcinoma (1 paper, 2023). A carcinoma arising from squamous epithelial cells. "To afford comparisons with previous data identifying GSK3β and PRMT-1 as regulating the phosphorylation of DP’s C-terminus, we initially chose to use the squamous cell carcinoma cell line SCC914." (PMID 37543698, 2023).
Stroke (1 paper, 2025). Sudden impairment of blood flow to a part of the brain due to occlusion or rupture of an artery to the brain. "DICAR/DICAR-JP has potential therapeutic benefits in stroke, which is mediated by the miR-361-5p/PRMT1 signaling pathway." (PMID 41446787, 2025).
cancer (164 papers, 2008 to 2026). A tumor composed of atypical neoplastic, often pleomorphic cells that invade other tissues. "Beyond differentiation, PRMT1 activity is intricately linked to the proliferative capacity of numerous cancer cells." (PMID 41256732, 2025). "Dysregulation of PRMT1 has been further associated with the pathogenesis of various diseases, including cancer, metabolic disorders, and immune dysfunction." (PMID 41256732, 2025). "Prior studies showed that type I PRMT and type II PRMT5 inhibitors are effective specifically in MTAP-deficient cells; yet, our data in MTAP-intact cancer cells show that targeting PRMT1 reduces persistence." (PMID 39699269, 2025). "Consistence with their increased expression levels and associations with poor clinical outcomes, PRMT1/4/5 showed cancer cell-growth dependencies." (PMID 38826355, 2025). "Modification of the Arg-3 residue of histone H4 (H4R3) by PRMT1 leads to pre-mRNA splicing and DNA signaling, which has been linked to cancers of the breast, colon, bladder, lung, and blood." (PMID 41301411, 2025). "PRMT1 expression and activation of the STAT3 signaling pathway was associated with poor prognosis and cancer recurrence in addition to tumor cell proliferation, differentiation, size, and migration, highlighting the essential role PRMT1 plays in tumorigenesis." (PMID 40001488, 2025). "Noteworthily, the overexpression of PRMT1 has been associated with the progression of various cancers through its transcriptional effects on carcinogenic factors." (PMID 40858547, 2025). "By inducing H4R3me2a, PRMT1 facilitates the expression of genes associated with the senescence-related secretory phenotype, blocking the sensitivity of cancer cells to CDDP." (PMID 38326807, 2024). "Recent studies have demonstrated that the dysregulation of PRMT1 is closely implicated in cancer initiation, progression, and poor prognosis in patients with cancer." (PMID 38474197, 2024). "The overexpression and aberrant splicing of PRMT1 are directly implicated in the development of several cancers, including breast, lung, and bladder cancers and leukemia." (PMID 39620228, 2024). "Numerous studies have demonstrated that PRMT1 is significantly expressed in different cancer types and is linked to tumor malignancy and prognosis." (PMID 38326807, 2024). "Overexpression of PRMT1 is observed in various types of human cancers and is associated with poor clinical prognosis." (PMID 37737256, 2023). "Alternative splicing of PRMT genes produces novel circRNAs implicated in several cancers, for example, splicing of the PRMT1 gene in breast cancer and circPRMT5 in non-small cell lung cancer and bladder cancer." (PMID 36144454, 2022). "Although cancer-associated mutations in PRMT1 are rare, its aberrant expression often correlates with poor outcome in various cancer types, including breast cancer." (PMID 35578032, 2022). "PRMT1-mediated methylation of arginine residues in transcription factors has been linked to cancer progression." (PMID 35941115, 2022). "This molecular circuit also contributes to higher activity of PRMT1 inhibitors in MTAP-deficient cancer cells." (PMID 35439169, 2022). "The three individual cancer mutations of PRMT1, i.e., W197L, Y202N, and M206V, were explored computationally by investigating the thermodynamic stabilization of near attack conformations (NACs) that resemble the transition state." (PMID 34688662, 2021). "Substantial differences exist between the three PRMT1 cancer-based mutations in terms of the probability of forming a NAC to yield MMA." (PMID 34688662, 2021). "Since PRMT1 dimerization is essential for activity, and aberrant arginine methylation seems to be significant in cancer pathology, we searched the COSMIC database for mutations in the PRMT1 dimerization arm." (PMID 34688662, 2021). "To clarify the molecular function of PRMT1 in mediating olaparib sensitivity, we analyzed associations between PRMT1 and the cancer hallmarks by using GSEA." (PMID 34683150, 2021).